GARIN4 (golgi associated RAB2 interactor family member 4)
Description:
RAB2B effector protein required for the compacted Golgi morphology, probably through interaction with small GTPase RAB2B.
Synonyms: GARI-L4; FAM71A; FLJ32796; GARIL4
Tractability: No criterion of Open Targets' tractability assessment is met for any kind of drug.
Gene: Protein-coding gene on chromosome 1 (212,624,474 to 212,626,775, forward strand). Ensembl gene ENSG00000162771.
Subcellular location: Golgi apparatus
Gene Ontology:
Molecular function: protein binding
Biological process: Golgi organization
Cellular component: Golgi apparatus; nucleus; sperm head
Genetic constraint (gnomAD): Loss-of-function variants: 0 observed, 0.29 expected, observed/expected ratio (o/e) 0, 90% interval 0 to 1.87. That is too few expected variants to judge how well the gene tolerates losing a copy. Missense variants: 763 observed, 806.25 expected, observed/expected ratio (o/e) 0.95, 90% interval 0.89 to 1. Synonymous variants: 302 observed, 306.25 expected, observed/expected ratio (o/e) 0.99, 90% interval 0.9 to 1.09.
Homologues: Orthologues: chimpanzee GARIN4 (96% identical), macaque GARIN4 (92% identical), rabbit GARIN4 (66% identical), dog GARIN4 (57% identical), rat Garin4 (51% identical), mouse Garin4 (51% identical). Paralogues in human: GARIN3 (48% identical), GARIN6 (23% identical), GARIN5B (21% identical), GARIN2 (16% identical), GARIN1B (11% identical), GARIN5A (11% identical), GARIN1A (10% identical).